ECM2 (extracellular matrix protein 2)
Description:
Promotes matrix assembly and cell adhesiveness.
Tractability: Antibody: its Gene Ontology location is reachable by antibodies, with high confidence; UniProt places it where antibodies can reach, with medium confidence; UniProt predicts a signal peptide or a membrane-spanning region; the Human Protein Atlas places it where antibodies can reach.
Gene: Protein-coding gene on chromosome 9 (92,493,554 to 92,536,736, reverse strand). Ensembl gene ENSG00000106823.
Subcellular location: Secreted, extracellular space, extracellular matrix
Subcellular location (Human Protein Atlas): Endoplasmic reticulum; Nucleoli fibrillar center; Predicted to be secreted
Gene Ontology:
Molecular function: collagen V binding; heparin binding; integrin binding; collagen binding; protein-containing complex binding
Biological process: cell-matrix adhesion; extracellular matrix organization; positive regulation of cell-substrate adhesion
Cellular component: extracellular matrix; gel phase of interstitial matrix; interstitial matrix
Genetic constraint (gnomAD): Loss-of-function variants: 48 observed, 60.89 expected, observed/expected ratio (o/e) 0.79, 90% interval 0.62 to 1. The upper end of that interval is the gene's LOEUF score, 1, which puts it in group 4 of 6, group 1 being the genes least tolerant of losing a copy. Missense variants: 708 observed, 825.93 expected, observed/expected ratio (o/e) 0.86, 90% interval 0.81 to 0.91. Synonymous variants: 248 observed, 296.21 expected, observed/expected ratio (o/e) 0.84, 90% interval 0.75 to 0.93.
Homologues: Orthologues: chimpanzee ECM2 (99% identical), macaque ECM2 (93% identical), rabbit ECM2 (79% identical), pig ECM2 (79% identical), dog ECM2 (78% identical), guinea pig ECM2 (77% identical), mouse Ecm2 (72% identical), rat Ecm2 (67% identical). Paralogues in human: LUM (16% identical), PRELP (16% identical), FMOD (15% identical), KERA (15% identical), OMD (14% identical), LINGO3 (12% identical), LINGO4 (12% identical), EPYC (10% identical), OGN (9% identical), OMG (9% identical).
Diseases named in the same sentence as ECM2 in open-access papers:
ECM2 is named in the same sentence as 16 diseases in open-access papers, as found by Europe PMC text mining. Sharing a sentence is not in itself a finding about the gene and the disease. The quoted sentences say what the papers report.
glioma (4 papers, 2019 to 2024). A benign or malignant brain and spinal cord tumor that arises from glial cells (astrocytes, oligodendrocytes, ependymal cells). "In this study, we found that ECM2 is significantly increased in gliomas and it is associated with the immune regulation in TIM." (PMID 37371331, 2023). "A high expression of ECM2 has been connected to glioma infiltration with immune cells and a short overall survival rate, which suggests a possible mechanism of immune cell recruitment by tumor cells." (PMID 39685635, 2024). "To further determine the biological function of ECM2, we utilized siRNAs to knockdown ECM2 in U87 and U251 glioma cell lines." (PMID 37371331, 2023). "Transwell assays showed the migration and invasion ability was consistently decreased in the U87 and U251 cell lines after ECM2 knockdown, indicating the important role of the ECM2 gene in the pathogenesis and development of gliomas." (PMID 37371331, 2023). "This is consistent with the results of in vitro functional experiments that high ECM2 expression promotes the proliferation, migration, and invasiveness of glioma cells." (PMID 37371331, 2023). "Our study provides a novel sight into understanding the role of ECM2 in glioma, which contributes to the development of new therapeutic strategies for glioma patients." (PMID 37371331, 2023). "In this study, we investigate the role of ECM2 in gliomas and its prognostic value for LGG patients." (PMID 37371331, 2023). "After the knockdown of ECM2, the functional experiments showed a significant decrease in proliferation, migration, and invasion in glioma cell lines." (PMID 37371331, 2023). "In this study, we found that ECM2 expression significantly increased with the grade of glioma, which has been confirmed by IHC results." (PMID 37371331, 2023). "Overall, our study suggests that ECM2 is a promising prognostic indicator and potential therapeutic target for glioma patients." (PMID 37371331, 2023). "It confirmed that ECM2 expression increased with the glioma grade." (PMID 37371331, 2023). "The expression levels of ECM2 in glioma were verified by IHC analyses in the HPA database." (PMID 37371331, 2023). "Extracellular matrix protein 2 (ECM2) has rarely been studied in gliomas." (PMID 37371331, 2023). "Furthermore, qRT-PCR, CCK-8, wound healing, and transwell assays were performed to confirm the function of ECM2 in gliomas." (PMID 37371331, 2023). "The function of ECM2 in glioma is confirmed with in vitro experiments." (PMID 37371331, 2023). "Although the in vitro experiments could verify the role of ECM2 in glioma cell lines, further in vivo experiments are necessary to reveal the effect of ECM2 on the pathogenesis and progression of glioma." (PMID 37371331, 2023). "For instance, ECM2 was related to immune process and could serve as a target for immunotherapy for glioma." (PMID 37507655, 2023). "However, there are few studies focused on the role of ECM2 in gliomas and its prognostic value for LGG patients is still unclear." (PMID 37371331, 2023). "The decreased proteins include proteins with known functions for glioma stemness and migration/invasion like CD9 (Gos, ATO/Gos), Ephrin receptor A2 (EPHA2; Gos, GANT/Gos) and mesenchymal (i.e., more aggressive) differentiation like FRAS1 related extracellular matrix protein 2 (FREM2; ATO/Gos)." (PMID 30871073, 2019).
breast carcinoma (2 papers, 2008 to 2024). "As HOXB2, MATN3, and ECM2 expressions positively correlated in breast cancer cells, we re-analyzed data from patient samples in publicly available clinical datasets of GSE65194 and GSE58812." (PMID 38322121, 2024). "Cluster 110 contains genes that have previously been associated with chemotaxis and invasion of breast cancer cell lines (SLIT2, RECK), as well as genes related to the extracellular matrix (ECM2, COL4A1)." (PMID 18498629, 2008). "Moreover, poor OS in patients with breast cancer was significantly associated with the concurrent downregulation of HOXB2, MATN3, and ECM2." (PMID 38322121, 2024). "Both MATN3 and ECM2 expressions were positively correlated with HOXB2 expression in the human breast cancer tissues." (PMID 38322121, 2024). "To further confirm the therapeutic efficacy of HOXB2/MATN3 or HOXB2/ECM2 transcriptional axis, we performed IHC for HOXB2, MATN3, and ECM2 in-house with 100 human tissue samples of patients with breast cancer." (PMID 38322121, 2024).
leiomyoma (2 papers, 2007). A well-circumscribed benign smooth muscle neoplasm characterized by the presence of spindle cells with cigar-shaped nuclei, interlacing fascicles, and a whorled pattern. "In contrast, the expression of EGR3, ECM2, THBS1, GAS1 and FBLN5 in scars and RUNX3 and COL18 expression in peritoneal adhesions was higher as compared to leiomyomas." (PMID 17718906, 2007). "We validated the expression of ECM-2, ESM1, THBS1, FBLN5 and COL18A1 in keloids, incisional scars and adhesions and the analysis indicated an elevated expression of ECM2, THBS1 and FBLN5 in keloid/incisional scars and COL18 in peritoneal adhesions as compared to leiomyomas." (PMID 17718906, 2007).
ovarian carcinoma (2 papers, 2010 to 2022). A malignant neoplasm originating from the surface ovarian epithelium. "Mone 1062—one of the mones in the identified cluster—was additionally highly correlated with ECM2, THBS1 and THBS2, which have been suggested to play a significant role in ovarian cancer drug resistance and metastasis." (PMID 35676395, 2022).
cardiac hypertrophy (1 paper, 2022). "Our data indicated that the expression of Ecm2 was decreased in E22K mice after performing exercise, indicating a beneficial effect of exercise on cardiac hypertrophy." (PMID 35265680, 2022).
hepatocellular carcinoma (1 paper, 2024). A malignant tumor that arises from hepatocytes. "The same trend of worse prognosis was observed in patients with lung cancer, renal clear cell carcinoma, or hepatocellular carcinoma exhibiting low HOXB2 and/or low HOXB2/MATN3/ECM2 expression." (PMID 38322121, 2024).
lymph node metastasis (1 paper, 2022). "The results suggest that the expression of ECM2, PCDH12, EPAS1, CD93, DLL4, and ARHGEF15 are significantly different in age, N (lymph node metastasis status), and whether radiotherapy is received or not." (PMID 35953532, 2022).
metastatic tumors (1 paper, 2024). "In particular, the expression of HOXB2, MATN3, and ECM2 was significantly suppressed in metastatic tumors compared to that in primary tumors." (PMID 38322121, 2024).
sarcoma (1 paper, 2025). A usually aggressive malignant neoplasm of the soft tissue or bone. "ECM2 and AMPH were associated with the prognosis of KIRC, and AMPH was a protective factor in PAAD and sarcoma (SARC)." (PMID 40433364, 2025).
tuberculosis (1 paper, 2025). A chronic, recurrent infection caused by the bacterium Mycobacterium tuberculosis. "Our results not only confirm the important role of A2M in active tuberculosis but also uncover a regulatory network involving A2M, F12, and ECM2." (PMID 41428679, 2025).
tumor (6 papers, 2019 to 2025). "ECM2 was elevated in tumor tissues of the majority of cancer types, whereas AMPH was frequently demonstrated." (PMID 40433364, 2025). "Therefore, we consider that ECM2 plays a potential role in the tumor immune microenvironment and affects the prognoses in LGG patients." (PMID 37371331, 2023). "Additionally, the same tumor subpopulation demonstrated a high expression of the ECM2 gene." (PMID 39685635, 2024). "Subsequent proteomic analysis revealed that several proteins, including extracellular matrix protein 2 (ECM2), MATN3, KIT ligand (KITLG), and proplatelet basic protein (PPBP), were overexpressed in the tumor-derived ECM." (PMID 39451244, 2024). "Tumor samples of Inserm series were predicted in 2 and 4 subtypes molecular classification using a predictor based on nine genes: ADAM19, ETS1, and PDCD1LG2 for C1 and C2; CLDN1, DSC3, and SLC24A3 for C1A and C1B; CHL1, ECM2, and PTPN13 for C2A and C2B subtype prediction." (PMID 32083805, 2020).
cancer (4 papers, 2021 to 2025). A tumor composed of atypical neoplastic, often pleomorphic cells that invade other tissues. "Of the many EMT- and ECM-associated factors, matrilin-3 (MATN3), and extracellular matrix protein 2 (ECM2) have been related to cancer metastases." (PMID 38322121, 2024). "Reduction of HOXB2 and the HOXB2/MATN3/ECM2 transcriptional axis correlated with poor survival in patients with various cancers." (PMID 38322121, 2024). "This is consistent with other EMT pathway genes in the skin; COMP, CTHRC1, ECM2, FBN1, LOX, and SPARC were all upregulated in samples with a mutation in a cancer gene." (PMID 36531005, 2022). "Additionally, our findings suggest that the lack of HOXB2 subsequently downregulates MATN3 and the ECM2 downstream transcriptional network, leading to aggressive cancer progression, EMT-like characteristics, and poor prognosis." (PMID 38322121, 2024).
ECM2 also shares sentences with these, for which no sentence is quoted: keloid (1 paper); lipid metabolic disorder (1); lung carcinoma (1); renal clear cell carcinoma (1).